IFNL4 (interferon lambda 4 (gene/pseudogene))
Diseases named in the same sentence as IFNL4 in open-access papers (continued):
Sharing a sentence is not in itself a finding about the gene and the disease.
liver disease (8 papers, 2013 to 2025). "The association of IFNL4[TT] genotype in patients with HCV‐related lymphoproliferative disorders was less evident than in patients with liver diseases." (PMID 32937024, 2021). "Here we demonstrate, using liver disease as a model, that a single-nucleotide polymorphism (rs12979860) in the intronic region of interferon-λ4 (IFNL4) is a strong predictor of fibrosis in an aetiology-independent manner." (PMID 25740255, 2015). "In the first place, TCGA gene expression results were found to support the concept of HCV exclusively being able to activate hepatic IFNL4 gene transcription, also in advanced liver disease." (PMID 34360569, 2021). "Other studies have reported complex relationships between IFNL4 and liver disease." (PMID 40823170, 2025). "We investigated the IFNL4 rs12979860 and the PDCD1 polymorphisms in 734 HCV‐positive patients, including 461 cases with liver disease of varying severity and 273 patients with lymphoproliferative disorders to determine the association of these genes with patient's outcome." (PMID 32937024, 2021). "Hence, our findings extend the association between genetic variation in the IFNL4 locus and outcome of HCV infection as well as hepatic disease." (PMID 31478835, 2019). "Accordingly, we examined potential confounding by demographic factors (i.e. age and sex), IFNL4 genotype, which was not available in previous studies, and a comprehensive suite of systematically measured clinical markers of liver disease." (PMID 27832143, 2016).
fibrosis (4 papers, 2016 to 2021). the formation of excess fibrous connective tissue in an organ or tissue in a reparative or reactive process. "Based on previous reports linking IFNL3/IFNL4 genotypes and fibrosis risk and our current results on association with cirrhosis risk in HCV patients, we explored molecular mechanisms that could explain these associations." (PMID 34497603, 2021). "With the identification of the IFNL4 TT/TT genotype as a potentially stronger predictor of SVR in the non-transplant setting, the present study was conducted to in order to confirm the suspected association of the donor IFNL4 polymorphism with early post-transplant fibrosis." (PMID 27875564, 2016). "Patients who developed early post-transplant fibrosis had a 3.45 adjusted odds of having donor IFNL4 TT/TT genotype (p = 0.012)." (PMID 27875564, 2016). "Donor IFNL4 TT/TT genotype, a favorable predictor of spontaneous HCV clearance pre-transplant, is associated with increased early post-transplant fibrosis and decreased survival." (PMID 27875564, 2016).
hepatocellular carcinoma (4 papers, 2013 to 2021). A malignant tumor that arises from hepatocytes. "IFNL4 additionally induces expression of rantes and fos genes in hepatoma cells." (PMID 28255563, 2017). "Furthermore, transient expression of IFNL4 was reported to activate expression of ISGs in hepatoma cells in vitro." (PMID 24376784, 2013). "Moreover, a transient overexpression of IFNL4 in hepatoma cells in vitro stimulated the expression of ISGs, which is consistent with the observation of a high baseline activation of ISGs in poor treatment responders." (PMID 24376784, 2013). "Hepatoma cell lines and PHH have also been used to study how the IFNL subtypes differ in their ability to limit viral infections; IFNL3 and IFNL4 induce the same set of ISGs in PHH and the two subtypes have the same antiviral activity against HCV in an overexpression setup in hepatoma cells." (PMID 28255563, 2017).
Hepatic fibrosis (2 papers, 2016 to 2024). The presence of excessive fibrous connective tissue in the liver. "Growing interest in exploring the role of IFN λ in liver fibrosis has stemmed from the discovery of an association between IFN λ SNPs and major IFNL3/IFNL4 with HCV clearance." (PMID 39201329, 2024). "The impact of IFNL4 polymorphisms on hepatic fibrosis has not been studied in the context of transplant." (PMID 27875564, 2016). "Confirmation of this finding is important as the functional role of IFNL4 is studied further at the basic science level and in the context of HCV-independent hepatic fibrosis." (PMID 27875564, 2016).
HIV-1 infection (2 papers, 2020 to 2022). The type species of lentivirus and the etiologic agent of acquired immunodeficiency syndrome (AIDS). "Present data confirms in an MSM population at high risk of infection, the involvement of IFNL4 in HIV-1 infection predisposition." (PMID 35481423, 2022). "In this context, functional IFNL4 possibly will induce a long-term insensitivity to interferon alpha, driving to weakened protection against HIV-1 infection." (PMID 35481423, 2022). "Whether expression of IFNL4 in HIV-1 infection modifies immune responses, particularly in those PLWH on effective ART, remains unclear, with contrasting observations reported." (PMID 32295609, 2020). "While IFNLs have been shown to skew T lymphocyte responses, their impact in treated HIV, in particular the potential for IFNL4 expression to modulate the CD4+:CD8+ T-cell ratio in the context of treated HIV-1 infection has not been explored to date." (PMID 32295609, 2020).
Obesity (2 papers, 2022). Accumulation of substantial excess body fat. "Other nominally significant associations were established between WHOCS scales and: IFNL4 rs12979860, ACEIs, obesity, ARA-II, HCP5 rs2395029, ACE rs1799752, DPP4 rs17574, HMOX1 rs2071746, IL10 rs1800896, IL6 rs1818879, NFKB1 rs28362491, and MX1 rs469390." (PMID 35636966, 2022).
pneumonia (2 papers, 2023 to 2025). An acute, acute and chronic, or chronic inflammation focally or diffusely affecting the lung parenchyma, caused by an infection in one or both of the lungs (by bacteria, viruses, fungi, or mycoplasma.). "Also, the authors observed that the likelihood of pneumonia development remained significantly associated with IFNL4 polymorphism, especially in females." (PMID 38288121, 2023).
prostate carcinoma (2 papers, 2020 to 2024). A carcinoma that arises from epithelial cells of the prostate gland. "For instance, the IFNL4 rs368234815 ΔG allele was shown to be associated with prostate cancer among men at increased risk of sexually transmitted infections." (PMID 33228589, 2020). "KSHV has been found to be associated with prostate cancer amongst those who carry the IFNL4 gene." (PMID 39655325, 2024). "The HHV-8 virus has been associated with both aggressive and non-aggressive prostate cancer amongst those carrying at least one G allele in IFNL4." (PMID 39655325, 2024).
respiratory infections (2 papers, 2021 to 2022). "More recently, it has also been reported that the IFNL4-dG allele is associated with reduced clearance of RNA viruses that cause respiratory infections." (PMID 33882912, 2021). "For example, a recent study conducted with children from Rwanda showed a reduced clearance of RNA viruses that cause respiratory infections in children carrying the IFNL4-dG allele." (PMID 33882912, 2021). "Carriage of the IFNL4-dG allele is clearly not providing protection against HCV, respiratory infections, gastrointestinal infections, human coronavirus, HCoV-229E or MERS-CoV, and now this study shows similar results for P. falciparum malaria in children." (PMID 33882912, 2021).
sexually transmitted infections (2 papers, 2020 to 2023). "The dinucleotide germline variant, rs368234815-ΔG, in the IFNL4 gene (IFNL4-ΔG) has been associated with prostate cancer among men at increased risk of sexually transmitted infections and reported to impair viral clearance." (PMID 35468990, 2023). "The present study also extends the observations from an earlier study that found the IFNL4-ΔG genotype to be associated with prostate cancer among men of an increased risk of sexually transmitted infections." (PMID 35468990, 2023).
autoimmune disease (1 paper, 2021). A disorder resulting from loss of function or tissue destruction of an organ or multiple organs, arising from humoral or cellular immune responses of the individual to their own tissue constituents. "Interferon‐lambda 4 (IFNL4) and programmed cell death protein‐1 (PD‐1) expression levels have emerged as important modulators of altered host response to HCV infection 4, 5, 6, 7 and as cause of a variety of autoimmune diseases." (PMID 32937024, 2021).
bronchiolitis (1 paper, 2019). Inflammation of the bronchioles characterized by swelling of the bronchioles and mucus accumulation. "IFNL4 variants have also been associated with bronchiolitis, cytomegalovirus and Andes virus infections." (PMID 31478835, 2019).
coinfection (1 paper, 2025). The simultaneous infection of a host by multiple pathogen species. "Overall, our data highlight that the emergence of potential high replicators can correlate also with clinical parameters beyond the LTX context like HIV coinfection or HCC as well as the genetic background of the IFNL4 gene." (PMID 40585217, 2025).
end-stage renal disease (1 paper, 2021). "Individuals who resolved HCV infection presented higher frequency of the IFNL4 rs368234815 TT/TT genotype, were older at RRT onset, had shorter RRT duration, less frequently demonstrated chronic glomerulonephritis as a cause of end-stage renal disease, and showed lower activities of liver enzymes." (PMID 34445971, 2021).
genital herpes (1 paper, 2015). Herpes simplex infection of the genitals, most commonly caused by the herpes simplex-2 virus. "The goal of our study was to investigate the association of IFNL4-ΔG/TT genotype with the frequency of oral and genital herpes episodes within the large prospective Women’s Interagency HIV Study (WIHS)." (PMID 26431156, 2015). "Self-reported and clinician-observed episodes of genital herpes among women enrolled in WIHS (both cohorts), by IFNL4 genotype and race." (PMID 26431156, 2015).
gonorrhea (1 paper, 2018). A common sexually transmitted bacterial infection caused by Neisseria gonorrhoeae. "Accordingly, we found that the association of gonorrhea with prostate cancer was stronger for IFNL4-TT/TT than IFNL4-ΔG carriers, arguing that the overall unfavorable association of IFNL4-ΔG with prostate cancer, as shown in our study, is more likely related to an infectious agent of viral origin." (PMID 30456312, 2018).
herpes labialis (1 paper, 2020). A lesion caused by type 1 or type 2 herpes simplex virus, typically involving the oralfacial region. "The polymorphism rs12979860 has been associated with the severity of recurrent herpes labialis and hepatitis C virus (HCV) clearance and treatment outcome and is located within the first intron of the IFNL4 gene on chromosome 19.q13.2." (PMID 33133009, 2020). "Since reactivation of a latent HSV-1 infection is discussed as a cause for VN and severity and recurrence rates of herpes labialis caused by HSV-1 infection are associated with rs12979860, a variation localized in the IFNL4 gene, an influence of this variation on VN pathology could be hypothesized." (PMID 33133009, 2020).
Hypertension (1 paper, 2024). The presence of chronic increased pressure in the systemic arterial system. "Multivariate logistic regression analysis revealed that age, history of DM or hypertension, blood urea, serum creatinine, FURIN (G/C + C/C) genotypes, and IFNL4 T/T homozygous were independent risk factors associated with increased mortality." (PMID 38703289, 2024).
influenza (1 paper, 2019). An acute viral infection of the respiratory tract, occurring in isolated cases, in epidemics, or in pandemics; it is caused by serologically different strains of viruses (influenzaviruses) designated A, B, and C, has a 3-day incubation period, and usually lasts for 3 to 10 days. "In influenza virus infection, IFNL4 SNP rs8099917 was associated with increased sero-conversion after influenza vaccination." (PMID 31478835, 2019).
liver cirrhosis (1 paper, 2021). "We also observed that HCV patients with IFNL4 genotype were less likely to manifest liver cirrhosis, in line with the previous studies." (PMID 34497603, 2021). "Thus, the interplay between the IFNL3/IFNL4 polymorphisms, HCV infection, and the risk of liver cirrhosis and HCC remains unclear." (PMID 34497603, 2021).
infection (12 papers, 2014 to 2022). The state of being infected such as from the introduction of a foreign agent such as serum, vaccine, antigenic substance or organism. "Our results strongly suggest that individuals carrying the rs368234815 IFNL4 T allele, which is a null allele of IFNL4, have less susceptibility to infection by HIV-1." (PMID 35481423, 2022). "IFNL4 mRNA could be detected in primary human hepatocytes (with the required single nucleotide polymorphism (SNP)) 2–4 h after stimulation with poly(I:C) and after in vitro infection with HCV." (PMID 26038748, 2014). "Our data demonstrate that gt1 infection drives a highly skewed type I IFN‐like response, which is apparently influenced by host IFNL4 genotype." (PMID 25800823, 2015). "Variation in IFNL4 did not significantly impact on the type of initial infection or viral or bacterial loads." (PMID 31637221, 2019). "The IFNL3/IFNL4 studies featured here were broadly not able to adjust for this duration of infection." (PMID 29397014, 2018). "Since the host response to HCV genotype 3a infection induces pathways including those affecting B cell development, we do not exclude the possibility that IFNL4 SNP rs12979860 genotype either influences B cell response to infection or the process of virus binding and entry." (PMID 31478835, 2019). "Despite the patient displayed favorable prognostic indicators—symptomatic course of infection, IL28B/IFNL4 CC genotype and HLA-B*27 expression—he did not succeed in clearing the virus and developed persistent low-level infection with HCV." (PMID 32183384, 2020).
infectious disease (5 papers, 2017 to 2022). A disorder directly resulting from the presence and activity of a microbial, viral, or parasitic agent in humans. "Single-nucleotide polymorphisms (SNPs) within the IFNL3/IFNL4 gene locus and impact on infectious diseases." (PMID 28293236, 2017). "Our results identified many novel variants located in essential genes to cancer (DPYD, TYMS, MTHFT, and GSTT1), infectious diseases (IFNL4), and psychiatric treatments (CYP2D6)." (PMID 35743738, 2022). "Given that the better response to HCV is probably not the evolutionary driver against the expression of IFNL4 protein, many studies in other infectious diseases have been conducted, but only a few reported associations with variants in the IFNL3 and IFNL4 region." (PMID 35208821, 2022). "In mice, commonly used as a model organism for infectious disease and immune function, only IFNL2 and IFNL3 are functional, as IFNL1 and IFNL4 are present as inactive pseudogenes." (PMID 28293236, 2017).
bacterial infection (3 papers, 2018 to 2022). "Thus, chronic viral infection in carriers of IFNL4-ΔG may lead to a decreased risk for a bacterial infection." (PMID 30456312, 2018). "This suggests that IFNλ4 with a lower activity could be beneficial during non-viral infections although a link between IFNL4 genotype and bacterial infection in humans has not yet been made." (PMID 30308076, 2018).
cancer (3 papers, 2018 to 2022). A tumor composed of atypical neoplastic, often pleomorphic cells that invade other tissues. "In our study, the IFNL4 rs368234815 ∆G/∆G genotype appeared to be associated with cancer mortality in HCV-exposed HD patients." (PMID 33482747, 2021). "To further explore a possible association between the IFNL4 rs368234815 ∆G/∆G genotype and mortality due to neoplasm, we genotyped not HCV-exposed HD patients who died from cancer in the analysed period, and their DNA samples were stored." (PMID 33482747, 2021).
tumor (3 papers, 2018 to 2021). "Once induced, IFN-λ4 protein may enhance negative regulation of IFN signaling, leading to impaired viral clearance and a distinct tumor biology in carriers of IFNL4-ΔG allele, as previously reported." (PMID 30456312, 2018). "By analyzing the whole set of tumor tissue samples, likewise, detectable levels of IFNL4 transcripts were present in a small portion of the samples only (56/371)." (PMID 34360569, 2021). "Additionally, such a survival analysis in the examined not HCV-exposed subjects did not reveal any relationship between neoplasm-related mortality and IFNL4 rs368234815 SNP." (PMID 33482747, 2021).
IFNL4 also shares sentences with these, for which no sentence is quoted: acute pancreatitis (1 paper); chronic hepatitis (1); chronic hepatitis B (1); G6PD deficiency (1); gastrointestinal infections (1); Genital ulcers (1); hepatitis B (1); liver inflammation (1); steatosis (1); Upper Respiratory Tract Infections (1); viral diseases (1).